TNF (tumor necrosis factor)
Diseases named in the same sentence as TNF in open-access papers (continued):
Sharing a sentence is not in itself a finding about the gene and the disease.
cancer (continued). "Together with chronic inflammation, there is an augmentation in the secretion of tumor necrosis factor (TNF) and the cytokine interleukin 6 (IL-6), which contributed to cancer development, progression and metastasis." (PMID 37374075, 2023). "Tumor necrosis factor α (TNFα) is a key mediator of cancer-related inflammation in RCCs, promoting a pro-tumoral milieu by inducing the production of reactive oxygen intermediates, cyclooxygenases, matrix metalloproteinases (MMPs), and cytokines." (PMID 37190141, 2023). "In several studies, this subtype showed a high TNF-, a pro-inflammatory cytokine closely related to oxidative stress responses and cancer progression." (PMID 36983633, 2023). "To characterize the polyfunctionality of cellular immune response, we also quantified IL-2 and TNF-α as T-cell-specific cytokines in a cohort of 50 HCWs and in all cancer patients." (PMID 37376576, 2023). "Individuals with IBD receiving immunosuppressive therapies (especially thiopurines and anti-TNF therapies) should receive regular screening and surveillance for potential treatment-related cancers where screening protocols exist." (PMID 37674502, 2023). "Their investigative focus encompassed a suite of biomarkers—activin A, growth differentiation factor 15 (GDF-15), IL-6, interleukin-1 beta (IL-1β), and tumor necrosis factor alpha (TNF-α)—which provided a comprehensive view of cancer cachexia’s unfolding." (PMID 37755304, 2023). "HBV replication not only enhanced the killing of cytotoxic T lymphocytes (CTL) and Kupffer cells to wipe out cancer cells, but activated cytokines such as TNF-α and INF-γ to boost the antitumor effects." (PMID 36910607, 2023). "Even more damaging to the concept of using recombinant TNF as a systemic cancer drug was the fact that its systemic application induced lethal inflammation." (PMID 36195672, 2023). "The anti-cancer effects of carnosine on U937 cells stem from the simultaneous increased expression of IL-1β, increased secretion of IL-10, GM-CSF, and TNFα, and decreased secretion of IL-8." (PMID 37998326, 2023). "TNF-α and IL-1β, cytokines with a pivotal action in both local and systemic inflammation, are of great importance in cancer development as it is involved in the regulation of cell proliferation and apoptosis." (PMID 37772231, 2023). "In the patients with a diagnosis of cancer, anti-TNF-exposed patients were matched (for cancer site, sex, age, and year of cancer diagnosis) with the non-anti-TNF-exposed patients." (PMID 36983432, 2023). "Research on the effect of RA on the release of TNF-α and cancer outcomes in experimental animal models is limited." (PMID 36765695, 2023). "FC exerted its therapeutic effect on UC primarily through IL-17 signaling pathway, TNF signaling pathway and Pathways in cancer." (PMID 37161415, 2023). "Differentiated M2-like TAMs are known to secrete pro-tumoral cytokines, such as CCL18, TNF-α, and matrix metalloproteinases, that can promote cancer progression." (PMID 36674955, 2023). "In this way, TNF-α is thought to act as a double-edged sword in either promoting or inhibiting cancer." (PMID 37212877, 2023). "Emerging clinical and preclinical evidence suggests that at least short courses of TNF inhibitors are safe for the treatment of irAEs in patients with cancer undergoing ICI therapy." (PMID 36836166, 2023). "Due to its systemic toxicity, methods of locally introducing TNFα to treat cancer have included isolated limb perfusion, viral vectors, and targeting peptides." (PMID 37461742, 2023). "PS exposure induction in cancer cells via these cytokines was verified by the treatment of the NHRI-HN1 cancer cells with TNF-α, IFN-γ, and Trail and analysis via flow cytometry." (PMID 37324949, 2023). "On the other hand, mast cell mediators, including TNF-α, IL-9, tryptase, histamine, granzyme B, and reactive oxygen specimens (ROS), have also been reported to mediate anti-cancer functions." (PMID 37445862, 2023).
cancer (continued). "Further, PS exposure due to the treatment of cancer cells with the condition media of CpG-2722-activated splenocytes was blocked via neutralizing antibodies against TNF-α, IFN-γ, and Trail or their combination." (PMID 37324949, 2023). "Many immunomodulatory natural products, such as flavonoids, flavones, phenolic compounds, and alkaloids, induce powerful anti-cancer efficacies via the modulation of NF-kB, iNOS, NO, Cox-2, and TNF-α." (PMID 38140352, 2023). "The indirect targeting of TNFα signaling through NF-κB inhibitors has also been more widely studied in cancers as NF-κB is frequently constitutively activated in most human cancers." (PMID 36980717, 2023). "Inflammatory cytokines, including TNF-α and IL-6, are responsible for cancer cachexia and are relevant to adipocyte transformation." (PMID 36672449, 2023). "The expressions of cancer-promoting factors, such as TNF-α, were also significantly down-regulated in the case of combination therapy." (PMID 37895145, 2023). "For example, higher levels of pro-inflammatory cytokines (e.g., IL-6, IL-8, TNFα) in peripheral blood before treatment were usually found to predict worse responses in various cancer types, including metastatic non-small-cell lung cancer and melanoma." (PMID 37887315, 2023). "Overall, it is recommended that patients who have already had cancer take TNF-α inhibitors with caution." (PMID 36836166, 2023). "Dysregulation of TNF-mediated ROS signaling is a characteristic of inflammatory diseases and cancers." (PMID 37827291, 2023). "The extract of the syringa leaves has shown strong antiproliferative properties against cancer cells, both in vitro and in vivo, via the induction of tumor necrosis factor-α (TNF-α) and the light-chain 3(LC3)-11 autophagosomal proteins." (PMID 37242968, 2023). "SMAC mimetics are therefore used in combination with drugs that stimulate the extrinsic (e.g. TRAIL, TNFα) or the intrinsic (e.g. chemotherapeutics) apoptotic pathways to enhance cancer cell death." (PMID 36845731, 2023). "On the other hand, proinflammatory CD68+ M1 macrophages are known to have antitumor effects, producing pro-inflammatory cytokines such as TNF-α to induce cancer cell apoptosis." (PMID 38037106, 2023). "Anti-TNF can be used in IBD patients with current cancer, according to the data from the Swedish observational cohort, which included 78,483 patients with RA treated with biologics (98% were anti-TNF)." (PMID 36983432, 2023). "TNF has been reported to be a pro-inflammatory factor that stimulates inflammation and plays a role in inhibiting infections and cancer processes." (PMID 37235433, 2023). "The cellular inhibitor of apoptosis 1 and 2 (c-IAP1 and c-IAP2) are known to play direct roles in apoptosis regulation in many cancers and also have been reported to regulate TNF-α-mediated NF-κB activation." (PMID 37867861, 2023). "No studies, however, directly explored the possibility that specific inhibition of Pol III activity sensitises cancer cells to TNFα." (PMID 36900285, 2023). "RIPK1 is highly expressed in KIRC and is upregulated by TNF-α, which further induces necrotic apoptosis of cancer cells through the RIPK1/RIPK3/MLKL/Drp1 axis." (PMID 37847185, 2023). "In a mouse model of cachexia, carnitine reduced the serum levels of IL-1 and IL-6, which are possible inducers of cancer cachexia, with slight effects on TNF-α." (PMID 37600065, 2023). "VEGF-A, TNF-α, CCL2, and IL-6 were positively associated with muscle-associated enzymes among the Cancer TIF1-γ-DM patients." (PMID 36357631, 2023). "The role that these cytokines, especially TNFα, play in cancer immune responses is still controversial." (PMID 37461742, 2023).
cancer (continued). "It was clear that pro-inflammatory cytokines were concentrated in HPNE spheroids, but cancer cells contributed to reducing the concentration of typical Th1 cytokines (e.g., TNF, IFN-y, IL-12)." (PMID 37519820, 2023). "The infiltration of immune cells related to almost all cancers is a source of secretion of inflammatory cytokines including IL-6 and tumour necrosis factor–alpha (TNF-alpha), which is an important link to cancer–inflammation interactions." (PMID 37753372, 2023). "TNF-α (tumor necrosis factor-alpha) has a paradoxical effect in cancer therapy; depending on the cellular and cytokines context, it induces either cancer cell death or survival." (PMID 37112810, 2023). "The effect of body temperature on the TNF-α release in cancer cell biology has been the subject of debate." (PMID 36765695, 2023). "Conversely, the top 200 pediatric B-ALL-exclusive EV RNAs showed pathways such as tumor-necrosis factor mediated signaling, choline metabolism in cancer, inositol phosphate metabolic process, platelet alpha granule lumen processes and protein deacetylation." (PMID 38023151, 2023). "TAMs produce growth-inducing hepatocyte growth factor, epidermal growth factor, TGF-β, and inflammatory IL-1β, IL-6, and TNF-α that can induce EMT in cancer cells." (PMID 36831498, 2023). "A significantly increased risk of cancer was observed in PID/SID patients and SOT/HSCT patients compared to TNF-i patients." (PMID 36624408, 2023). "CRP is subject to regulation by key molecular triggers of cachexia, such as IL-6, IL-1β, and TNF-α, which not only promote cancer cell growth and safeguard cancer cells against apoptosis but also stimulate angiogenesis and metastasis." (PMID 37755304, 2023). "Exercise intervention studies have reported results on the reduction of inflammatory biomarkers associated with cancer including C-reactive protein (CRP), interleukin-6 (IL-6) and tumor necrosis factor-α (TNF-α)." (PMID 35779184, 2023). "Our work demonstrated that PD inhibited GC cell proliferation and induced apoptosis via the PI3K–AKT signaling pathway, IL-17 signaling pathway, and TNF signaling pathway, which provide valuable evidence of the role of PD in cancer development." (PMID 37361599, 2023). "HDGF controlled the growth of each organoid in a species-specific manner of H. pylori, but TNFα decreased the cell viability in H. pylori-infected cancer organoids." (PMID 37047540, 2023). "While this is most likely the case, no studies have directly explored the possibility that specific inhibition of Pol III activity sensitises cancer cells to TNFα." (PMID 36900285, 2023). "In cancer cachexia, NF-κB also suppresses the expression of MyoD, a muscle-regulatory factor, at the transcriptional level after the activation of TNF-α." (PMID 37217930, 2023). "Dual-RevCAR T-cells secreted increased amounts of GM-CSF, IFN-γ, IL-2 and TNF-α only upon engaging CEA+ EpCAM+ cancer cells upon simultaneous presence of anti-CEA and anti-EpCAM RevTMs." (PMID 38169746, 2023). "The expression of the Zta gene leads to reduction of TNF-R1 and inhibition of TNF-α, which is an important factor in the induction of apoptosis in cancer cells." (PMID 37736518, 2023). "We previously reported targeted delivery of TNFα to tumors in experimental mouse models of cancer and pet dogs with natural cancers." (PMID 37331004, 2023).
cancer (continued). "Secondly, the TNF signalling pathway is particularly relevant as TNF-alpha is known to drive remodelling of blood vessels and has multiple roles in angiogenesis, which is known to be related to cancer and immunity." (PMID 36817116, 2023). "TNFα treatment alone very rarely induces cancer cell death, as the cells acquire resistance to this cytokine." (PMID 36900285, 2023). "Macrophages cultured with the estrogen receptor-positive (ER+) cancer cell line T47D also expressed more TNFα." (PMID 37445941, 2023). "The important parts of cancer research are TNF signaling pathway (hsa04668) and pathways in cancer (hsa05200)." (PMID 37869102, 2023). "Worth to be noted, among these designs a second-generation oncolytic HSVs expressing TNF-α are being developed for cancer therapy and exerting its high efficacy for cancer therapy." (PMID 37491263, 2023). "For example, CAFs and cancer cells communicate bidirectionally through secreting of inflammatory cytokines such as IL-1A, IL-1B and Tumor Necrosis Factor (TNF)." (PMID 37666813, 2023). "They suppress innate and adaptive immune systems, including suppressing of T-cells through prostaglandin E2, CXCL9, CXCL10, and CXCL11, and nitric oxide synthase in response to cancer cell-secreted TNFα, IFNγ, and IL-1." (PMID 37046676, 2023). "Of these targets, CDCP1 is reportedly associated with PI3K/AKT signaling, CMTM6 is a critical regulator of PD-L1 in a broad range of cancer cells, while UBE2D3 is linked to NF-κB signaling and ADAM10 plays a role in TNF signaling." (PMID 38041015, 2023). "KEGG enrichment analysis indicated that the activated pathways included HIF, pathways in cancer, TNF, PI3K‐AKT, mTOR, TGF‐β, cell cycle, and MAPK signaling." (PMID 37085918, 2023). "Kupffer cells and LSECs also express TNFα, nitric oxide (NO), and reactive oxygen species (ROS), which can induce cancer cell death." (PMID 37371127, 2023). "T helper 1 (Th1) cells primarily secrete cytokines, such as interferon (IFN)-γ and tumor necrosis factor (TNF)-α, which can enhance the body’s autoimmune response and are important anti-cancer therapeutic agents." (PMID 36978120, 2023). "Twelve components were included in the MAPK signalling pathway, and of these, EFNA3, STMN1, PAK1, and TNF have previously been found to regulate EMT in cancer progression." (PMID 37225681, 2023). "Tumor necrosis factor (TNF) and TNF receptors superfamily members play a role in the pathogenesis of various diseases including cancer." (PMID 37173331, 2023). "Initially, TNF was considered a potential treatment drug for cancer, followed by the opposite concept of targeting TNF for inflammatory diseases." (PMID 38022554, 2023). "Tumor necrosis factor alpha inhibitors, such as infliximab and etanercept, have been widely evaluated in clinical trials for various cancers and have shown promising results." (PMID 37711747, 2023). "Elevated systemic levels of IL-6, IL-1, and TNF-α in cancer patients seem to correlate with the progression of tumors." (PMID 37755304, 2023). "Tumor necrosis factor (TNF) and cathepsin G derived from neutrophils promote distant metastasis of malignant tumors." (PMID 37143476, 2023). "Tumor necrosis factor-α (TNFα) is a cytokine that has a complex role in inflammation and cancer pathology." (PMID 37958474, 2023).
cancer (continued). "While these anti-inflammatory agents targeting TNF-α and IL-6 have shown some positive results, further research is needed to fully understand their clinical efficacy in treating cancer cachexia." (PMID 37755304, 2023). "KEGG pathway enrichment analysis showed that these hub genes highly participated in IL-17 signaling pathway, TNF signaling pathway and Pathways in cancer, indicating the multi-targets and multi-channels regulation of FC in UC treatment." (PMID 37161415, 2023). "The subnetworks of ATF4, PIK3R1, and PIK3R3 filtered out from our study have been also shown to participate in TNF signaling pathway, since these hub genes involve immune regulation in cancer and AR disease." (PMID 37430199, 2023). "It was proposed that whereas low TNF levels support the growth of cancer, high TNF levels are antitumoral." (PMID 38139369, 2023). "NK cells are abundant in the liver where they prevent cancer cells from invading the liver and induce cancer cell death through a variety of cytotoxic pathways, including particle-mediated, FasL-mediated, and TNF-mediated apoptosis." (PMID 37138880, 2023). "Upon exposure to TNFα, cancer cells increase their expression of TF and produce TF‐bearing microparticles with potent local pro‐coagulant effects." (PMID 37795779, 2023). "IL-6 and TNF-α induce the proliferation of oval cells, which are putative cancer progenitor cells that appear in severe liver injury." (PMID 37896221, 2023). "The TNF-α was evaluated in cell culture media using an ELISA and cancer cell apoptosis was performed." (PMID 36802384, 2023). "In summary, this study demonstrated a link between TNFα-mediated inflammation and cancer metabolism." (PMID 36923932, 2023). "Moreover, TNF-α could associate inflammation with cancer in DM." (PMID 36357631, 2023). "KEGG analysis indicated that DEIRGs were mainly enriched in cytokine–cytokine receptor interaction, TNF signaling pathway, and proteoglycans in cancer." (PMID 37373979, 2023). "The advantage of adenovirus-based gene therapy is the ability to target TNF directly in cancer cells by limiting viral replication in healthy cells." (PMID 37046608, 2023). "To date, most safety data come from RA studies, in which MACE and cancer rates were increased with the use of tofacitinib compared to anti-TNF agents." (PMID 36936239, 2023). "The anti‐cancer activity of PPIs is based on the fact that it can significantly reduce the production of acid‐active substances, IL‐6 and nitric oxide, especially TNF‐α, expression of inducible NOS and COX‐2." (PMID 35961680, 2023). "On one hand, T cells have anticancer activity: CD8+ T cells decrease the viability of cancer cells, and Th1 cells secrete pro-inflammatory factors like TNF-α and IFN-γ, which stimulate the immune system against cancer cells." (PMID 37736898, 2023). "Hence, a more in-depth investigation into the function of cytokine-induced inflammation and cancer-associated muscle atrophy, with a particular focus on the participation of TNF-α, IL-1, IL-6, and IFNγ, could yield significant knowledge regarding the fundamental mechanisms involved." (PMID 37959329, 2023). "Regarded as having anticancer activity, TNF mediates the inflammatory response and regulates immune function to induce apoptosis of cancer cells." (PMID 37212877, 2023). "In ccRCC, cancer-cell-derived factors such as IL-1β, IL-6, IL-10, tumor necrosis factor-α, epidermal growth factor, and TGF-β induce macrophage polarization towards a M2 phenotype by cell-cell interactions." (PMID 37842234, 2023). "M1 macrophages produce ROS, nitric oxide (NO), and pro-inflammatory cytokines, such as interleukin-6 (IL-6), IL-12, and tumor necrosis factor-α (TNF-α), which participate in the inflammatory response and suppress cancer." (PMID 37241759, 2023).